ENSG00000288751 (novel transcript)
Gene: Long non-coding RNA gene on chromosome 6 (33,207,081 to 33,208,638, reverse strand). Ensembl gene ENSG00000288751.
Gene Ontology:
Biological process: miRNA-mediated post-transcriptional gene silencing
Cellular component: RISC complex